CYP3A5 (cytochrome P450 family 3 subfamily A member 5)
Diseases named in the same sentence as CYP3A5 in open-access papers (continued):
Sharing a sentence is not in itself a finding about the gene and the disease.
colon cancer (2 papers, 2007 to 2011). "Minor differences in the frequencies for individuals carrying the CYP3A4*1A plus CYP3A5*3 haplotypes were observed in some subgroups of gastric or colon cancer, as compared to healthy subjects, with p values under 0.05." (PMID 17605821, 2007). "Moreover, we show that LS180 colon cancer cells that overexpress SXR are less sensitive to CPT-11 treatment compared to control cells, indicating that this transcription factor is involved in drug resistance, probably through CYP3A4, CYP3A5, MDR1 and MRP1 upregulation." (PMID 21733184, 2011).
depression (2 papers, 2016 to 2022). "This network consisted of a number of molecules previously reported to be associated with depression (according to a PubMed search), such as CYP3A5, VAMP2, CSGALNACT1, CASP8, CRHR2, PKD2, and OXT." (PMID 26728011, 2016).
dyslipidaemia (2 papers, 2021 to 2024). "After adjusting for potential confounding factors, CYP3A5*3/*3 genotype, adjustments to antihypertensives, young age, dyslipidaemia, smoking and use of TCM were found to be factors associated with rapid CKD progression." (PMID 33808503, 2021).
gastric cancer (2 papers, 2007 to 2021). A primary or metastatic malignant neoplasm involving the stomach. "Gastric cancer patients who were CYP3A4*22 carriers had higher rates of toxicity (58%) compared to non-carriers who were homozygous for CYP3A5*3 (41%) and non-carriers heterozygous for CYP3A5*3 (17%)." (PMID 35174070, 2021).
glioblastoma (2 papers, 2024 to 2025). The most malignant astrocytic tumor (WHO grade IV). "We found that in kidney renal papillary cell carcinoma, pancreatic adenocarcinoma, kidney renal clear cell carcinoma, glioblastoma multiforme, and skin cutaneous melanoma, CYP3A5 expression was higher in tumor tissues than in normal tissues." (PMID 38560501, 2024). "Furthermore, CYP3A5 was upregulated in GSCs maintained under serum-free conditions compared with differentiated glioblastoma adherent cells (DGCs) cultured in serum-supplemented medium." (PMID 39754188, 2025).
hepatitis C (2 papers, 2021 to 2022). "A study by R. Tsunedomi revealed that CYP3A5 expression is dramatically reduced during venous invasion in patients with hepatitis C–associated hepatocellular carcinoma (hepatitis C–associated HCC)." (PMID 36359206, 2022).
kidney failure (2 papers, 2013 to 2024). An acute or chronic condition that is characterized by the inability of the kidneys to adequately filter the blood. "Compared to carriers of CYP3A5*1, kidney failure patients harboring the CYP3A5*3 form were reported to be associated with increased risk of early renal glomerular injury upon receiving a kidney transplant." (PMID 39080672, 2024). "This study sought to determine single nucleotide polymorphisms in CYP3A5, CYP3A4 and MDR1 genes that affect the pharmacokinetics of Tacrolimus in a population of Ghanaian patients with kidney failure." (PMID 39080672, 2024). "This study described the allele and genotype frequencies of SNPs in CYP3A5, CYP3A4, and MDR1 genes that affect the pharmacokinetics of Tacrolimus in a population of Ghanaian patients with kidney failure." (PMID 39080672, 2024). "SNPs in CYP3A4, CYP3A5, and MDR1 genes in a population of Ghanaian kidney failure patients were described." (PMID 39080672, 2024). "Most of the kidney failure patients in the present study harbored SNPs of CYP3A4, CYP3A5, MDR1 C3435T, and MDR1 G2677T, that could affect tacrolimus dose requirement in transplant recipients." (PMID 39080672, 2024).
lung adenocarcinoma (2 papers, 2022 to 2023). A carcinoma that arises from the lung and is characterized by the presence of malignant glandular epithelial cells. "For the estimation of patients’ paclitaxel-metabolizing capacity, CYP2C8, CYP3A4 and CYP3A5 alleles (CYP2C8*3, CYP2C8*4, CYP3A4*1B, CYP3A4*22, CYP3A5*3) most common in Caucasian populations were identified in lung adenocarcinoma patients on paclitaxel therapy (N = 17)." (PMID 37686184, 2023). "They demonstrated by RT-PCR, Western blotting, and immunohistochemistry that CYP3A5 is usually downregulated in lung adenocarcinoma (LUAD) tissues and cell lines." (PMID 36359206, 2022). "In lung adenocarcinoma A549 cells, CYP3A5 is activated by glucocorticoids via a GR." (PMID 36359206, 2022).
medulloblastoma (2 papers, 2021 to 2022). A malignant, invasive embryonal neoplasm arising from the cerebellum. "HIF1α promoted drug resistance in human medulloblastoma by inhibition of CYP2B6, CYP3A4 and CYP3A5 expression, which in turn resulted in decreased conversion of CPA and IFA into their active forms and thus to diminished cytotoxicity." (PMID 35355718, 2022). "In 82.3 cells, we observed overexpression of HIF1A; in medulloblastoma, the upregulation of HIF1A correlated with a worse response to cyclophosphamide through the inhibition of a gene of the cytochrome p450 family, CYP3A5, also found to be down-regulated in our model." (PMID 33922695, 2021).
membranous nephropathy (2 papers, 2019 to 2024). "The current research aimed to investigate the correlation between the effect of Wuzhi soft capsule (WZC) on FK506 concentration and CYP3A5 gene polymorphism in patients with membranous nephropathy (MN)." (PMID 31770256, 2019). "The study aimed to systematically evaluate the relationship between CYP3A5*3 gene polymorphisms and the blood concentration and effectiveness of tacrolimus (TAC) in patients with membranous nephropathy (MN)." (PMID 38835664, 2024). "Therefore, when using TAC to treat MN, detecting the CYP3A5 * 3 gene polymorphism in patients can assist clinicians in determining the optimal initial dosage so as to achieve effective blood drug concentration in a shorter time and, thus, optimize the management of membranous nephropathy." (PMID 38835664, 2024).
nephrotic syndrome (2 papers, 2021 to 2025). A collection of symptoms that include severe edema, proteinuria, and hypoalbuminemia; it is indicative of renal dysfunction. "Renal transplant pediatric patients with CYP3A5 non-expressers suffering from nephrotic syndrome showed a higher blood concentration of tacrolimus than CYP3A5 expressers after one-week WZC use." (PMID 33673653, 2021).
pancreatic ductal adenocarcinoma (2 papers, 2024 to 2025). An infiltrating adenocarcinoma that arises from the epithelial cells of the pancreas. "CYP3A5 has been proposed to be a key mediator of both intrinsic and acquired chemoresistance in pancreatic ductal adenocarcinoma, possibly because of its involvement in tumor cell-autonomous drug detoxification." (PMID 39754188, 2025). "Taken together, our results, for the first time, reveal a role of CYP3A5 in glucose metabolism in pancreatic ductal adenocarcinoma and identify a novel mechanism that is a potential therapeutic target." (PMID 38560501, 2024). "In this report, we demonstrate that CYP3A5 regulates glucose metabolism in pancreatic ductal adenocarcinoma." (PMID 38560501, 2024). "It has been reported that CYP3A5 is overexpressed in pancreatic ductal adenocarcinoma (PDAC) and mediates chemoresistance in different subtypes of this cancer." (PMID 38560501, 2024). "CYP3A5 was reported to mediate therapy resistance in pancreatic ductal adenocarcinoma." (PMID 39754188, 2025).
soft tissue sarcoma (2 papers, 2014 to 2022). A malignant neoplasm arising from muscle tissue, adipose tissue, blood vessels, fibrous tissue, or other supportive tissues excluding the bones. "Higher expression of CYP3A4 and CYP3A5 than in adjacent normal tissues has been reported in studies on rhabdomyosarcoma, which is the most common soft tissue sarcoma in children." (PMID 36359206, 2022). "Using standard inmunohistochemical methods, CYP3A4/CYP3A5 enzymes have been previously identified in various types of malignant tumors, including soft tissue sarcomas and osteosarcoma." (PMID 24699256, 2014).
Stroke (2 papers, 2017 to 2022). Sudden impairment of blood flow to a part of the brain due to occlusion or rupture of an artery to the brain. "CYP3A5 expressors had a numerically higher BMI (28.1 vs. 27.1; p = 0.10) and a numerically higher prevalence of prior stroke or TIA (4.1% vs. 2.2%; p = 0.10)." (PMID 36545312, 2022).
systemic lupus erythematosus (2 papers, 2017 to 2024). An autoimmune multi-organ disease typically associated with vasculopathy and autoantibody production. "The purpose of this study was to describe the impact of sex and cytochrome P450 3A5 (CYP3A5) variant on the blood concentration of tacrolimus in patients with systemic lupus erythematosus or rheumatoid arthritis." (PMID 28324194, 2017).
tuberculosis (2 papers, 2011 to 2012). A chronic, recurrent infection caused by the bacterium Mycobacterium tuberculosis. "Comparisons of CYP2B6, CYP3A5, NAT2, SLCO1B1 and ABCB1 variant alleles and genotype/haplotypes between DILI non-DILI cases among HIV patients with or without tuberculosis." (PMID 22808112, 2012). "Hence concomitant uses of these drugs exacerbate the incidence of DILI, ii) anti-tuberculosis drugs mainly rifampicin induces CYP2B6 and CYP3A5 lowering efavirenz plasma concentration while isoniazid inhibits some CYP enzymes." (PMID 22162992, 2011).
ulcerative colitis (2 papers, 2020). An inflammatory bowel disease involving the mucosal surface of the large intestine and rectum. "We previously reported that the incidence of adverse events in ulcerative colitis patients treated with tacrolimus was significantly higher in CYP3A5 expressers than non-expressers." (PMID 32993151, 2020).
acute leukemia (1 paper, 2015). A clonal (malignant) hematopoietic disorder with an acute onset, affecting the bone marrow and the peripheral blood. "Genotype frequencies of CYP1B1, CYP3A5, GSTT1, GSTM1 and SULT1A1 in males and early age acute leukemia, Brazil, 2000–2012." (PMID 25992585, 2015). "Genotype frequencies of CYP1B1, CYP3A5, GSTT1, GSTM1 and SULT1A1 in females and early age acute leukemia, Brazil, 2000–2012." (PMID 25992585, 2015).
acute myeloid leukemia (1 paper, 2023). Acute myeloid leukemia (AML) is a group of neoplasms arising from precursor cells committed to the myeloid cell-line differentiation. "The results showed that the frequency of CYP3A5*3 was higher at 81.5% in acute myeloid leukemia cases compared to controls." (PMID 37759317, 2023).
angina (1 paper, 2023). "Incident MI/angina was less likely to occur in patients heterozygous for CYP3A5 rs776746 compared to CC homozygotes (P = .01)." (PMID 36134646, 2023).
asthenia (1 paper, 2023). Clinical sign or symptom manifested as debility, or lack or loss of strength and energy. "At allele level, the G allele for rs2242480 (CYP3A4, p = 0.02) and the C allele for rs776746 (CYP3A5, p = 0.022) were also associated with grade 1 of asthenia." (PMID 36982571, 2023).
Azoospermia (1 paper, 2024). Absence of any measurable level of sperm,whereby spermatozoa cannot be observed even after centrifugation of the semen pellet. "The remaining annotations covered polymorphic pseudogenes either linked to a provisional phenotype (e.g. GUF1), or multifactorial diseases (e.g. CYP3A5), or with late onset diseases such as macular degeneration (e.g. ARMS2), retinitis pigmentosa and azoospermia or oligospermia, OR2W3." (PMID 39488654, 2024).
bile duct cancer (1 paper, 2024). "This showed that cell lines derived from colorectal, kidney, stomach, pancreas, or bile duct cancers had higher CYP3A5 expression than did other cancer cell lines." (PMID 38560501, 2024).
cardiomyopathy (1 paper, 2025). A disease of the heart muscle or myocardium proper. "The CYP3A5-rs4646450-TT and the SLC28A3- rs7853758-AA genotypes were associated respectively with a 6.6-fold (95% CI: 1.7–25.7, p = 7.00 × 10−3) and 9.8-fold (95% CI: 1.7–56.0, p = 0.01) increased risk of cardiomyopathy." (PMID 40413218, 2025).
cholangiocarcinoma (1 paper, 2015). A carcinoma that arises from the intrahepatic biliary tree (intrahepatic cholangiocarcinoma) or from the junction, or adjacent to the junction, of the right and left hepatic ducts (hilar cholangiocarcinoma). "The expression pattern obtained here, with CYP3A5 down-regulation expression gene (cytochrome P450 family) and LGALS3 up-regulation expression gene (galectine 3), could also be used to explain the lack of association between infection with F. hepatica and cholangiocarcinoma." (PMID 26247779, 2015).
colon adenocarcinoma (1 paper, 2020). "In particular, G. biloba extract at 200 μg/mL increased by 9.5-fold human PXR activation and the expression of PXR target genes, i.e., CYP3A4, CYP3A5 and ABCB1 (encoding P-gp) in human LS180 colon adenocarcinoma cells." (PMID 32635538, 2020).
colonic adenomas (1 paper, 2005). "Western blot analyses of CYP2E1, CYP3A4, and CYP3A5 were performed with specimens obtained from 25 patients with colonic adenoma and 27 disease-free controls." (PMID 16281975, 2005). "However, in the present study protein levels of CYP2C8, CYP3A4, and CYP3A5 were found to be significantly lower in normal unaffected colonic mucosa of patients with colonic adenoma in comparison with disease-free controls." (PMID 16281975, 2005). "Therefore, the aim of the present study was to determine expression and protein concentrations of four representative CYPs (e.g. CYP2C, CYP2E1, CYP3A4, and CYP3A5) in macroscopically normal colonic tissue of subjects with and without colonic adenomas." (PMID 16281975, 2005).
colorectal adenocarcinoma (1 paper, 2016). The most common type of colorectal carcinoma. "HT-29 colorectal adenocarcinoma cells also showed higher expression of CYP3A5 than that of CYP3A4." (PMID 27119350, 2016).
COVID-19 (1 paper, 2021). A disease caused by infection with severe acute respiratory syndrome coronavirus 2. "Variants in CYP3A4, CYP3A5, CYP2C8, CY2D6, ABCB1, ABCC2, and SLCO1B1, among other variants, could be included in pharmacogenetic studies of COVID-19 treatment." (PMID 33807592, 2021).
diffuse large B-cell lymphoma (1 paper, 2018). "CYP3A5 rs776746 AG/AA seemed to increase the risk of grade 2–4 cardiac toxicity in diffuse large B-cell lymphoma patients." (PMID 29970035, 2018).
glioma (1 paper, 2025). A benign or malignant brain and spinal cord tumor that arises from glial cells (astrocytes, oligodendrocytes, ependymal cells). "The general expression status of CYP3A5 was subsequently evaluated in association with various clinical and molecular characteristics among glioma patients." (PMID 39754188, 2025). "Among four candidates, CYP3A5 expression is associated with the poorest prognostic outcomes according to a single covariate Cox proportional hazards model in glioma patients." (PMID 39754188, 2025). "In this study, we identify a novel GSC target CYP3A5 based on the glioma stemness-related score system GScore." (PMID 39754188, 2025). "Additionally, CYP3A5 expression is higher in highly aggressive DNA methylation-based glioma subtypes." (PMID 39754188, 2025). "Collectively, our findings suggest that CYP3A5 may serve as a promising druggable target for glioma patients with high stemness status." (PMID 39754188, 2025). "We found that the CYP3A5 expression level was positively correlated with the expression of most stemness-related genes, as supported by the analysis of bulk transcriptomic data of gliomas in TCGA and CGGA cohorts." (PMID 39754188, 2025). "Since STAT3 has been reported as a TF associated with glioma stemness, we next tested whether STAT3 promoted CYP3A5 transcription." (PMID 39754188, 2025). "Notably, CYP3A5 expression escalates with increasing the WHO grades of glioma, as supported by the results of immunohistochemical (IHC) staining of the glioma tissue microarray, as well as the mRNA expression data from TCGA glioma and glioma samples of our center." (PMID 39754188, 2025). "In the glioma cell line, we found that CYP3A5 depletion had the lowest normalized connectivity score, suggesting the strongest ability to reverse the high GScore signature for glioma." (PMID 39754188, 2025).
Headache (1 paper, 2025). Cephalgia, or pain sensed in various parts of the head, not confined to the area of distribution of any nerve. "Demographic factors may also contribute; women and younger adults tend to experience medication-related headaches more frequently due to hormonal and vascular factors, while racial differences in CYP3A4 and CYP3A5 metabolism may underlie variable adverse effect profiles." (PMID 41562805, 2025).
Hyperkalemia (1 paper, 2021). An abnormally increased potassium concentration in the blood. "In contrast, aldosterone is normally secreted in response to hyperkalemia, and therefore the shunting of glucocorticoids to the MR pathway by CYP3A5 during elevated stress could potentially disrupt innate K + feedback loops required to prevent hypokalemia." (PMID 33633318, 2021).
intestinal cancer (1 paper, 2016). "Relative amounts of mRNA expression of CYP3A5 was much higher than those of CYP3A4 mRNA in HCT-8 human intestinal cancer cells that originates from ilocecum." (PMID 27119350, 2016). "By contrast to the impacts of OTA, AFB1 led to marginal changes of expression of CYP3A4 whereas it had partially suppressive effects on CYP3A5 mRNA expression in both intestinal cancer cells." (PMID 27119350, 2016). "However, OTA treatment increased CYP3A4 mRNA expression, but decreased CYP3A5 mRNA expression in both intestinal cancer cells." (PMID 27119350, 2016).
Jaundice (1 paper, 2022). Yellow pigmentation of the skin due to bilirubin, which in turn is the result of increased bilirubin concentration in the bloodstream. "At each HCT level, TBIL was set to four levels (<17.1, 17.1–85.5, 85.5–171, and >171 μmol L−1) according to the severity of jaundice, and the recipients were divided into poor (CYP3A5*3*3) and intermediate metabolizers (CYP3A5*1*3 or CYP3A5*1*1)." (PMID 36438793, 2022).
kidney injury (1 paper, 2016). Trauma to the kidney. "Our study suggests that co-administration of fluconazole with Tac-QD in the CYP3A5*3/*3 may cause not only elevation of tacrolimus blood concentrations but also kidney injury." (PMID 27217047, 2016).
liver dysfunction (1 paper, 2020). "In our present study, the incidence of liver dysfunction in stable liver transplant recipients converted to once-daily extended-release tacrolimus was higher in the CYP3A5 expressor group than in the non-expressor group." (PMID 32911703, 2020).
liver failure (1 paper, 2020). A liver disease characterized by the liver losing or has lost all of its function. "Therefore, numerous examples of toxicant metabolism involving CYP3A5*1 can be found in the literature, such as acetaminophen-related liver failure caused by the accumulation of its toxic metabolite N-acetyl-p-benzoquinone-imine (NAPQI)." (PMID 33291741, 2020).
liver toxicity (1 paper, 2018). "The role of CYP3A4 and CYP3A5 variants in determining NVP plasma concentration and the development of liver toxicity is more controversial, with only one report of association between CYP3A5 variants and transaminase values in African patients exposed to NVP." (PMID 30419834, 2018).
lung squamous cell carcinomas (1 paper, 2020). "Rs10242455 in CYP3A5 gene showed significant difference between the two groups in lung squamous cell carcinoma (rs10242455: P = 0.018, OR 0.71, 95% CI 0.53–0.94)." (PMID 32350633, 2020).
metastatic colorectal cancer (1 paper, 2020). "A total of 132 metastatic colorectal cancer patients were genotyped for CYP3A4*1B, CYP3A4*18, CYP3A5*3, DPYD*2A, DPYD*5, DPYD c.1774C > T, UGT1A1*28, UGT1A1*6, ABCB1 c.1236C > T, ABCB1 c.3435C > T, ABCC2 c.3972C > T, and ABCG2 c.421C > A." (PMID 32778670, 2020).